MIR548AH (microRNA 548ah)
Synonyms: hsa-mir-548ah
Gene: MicroRNA gene on chromosome 4 (76,575,551 to 76,575,626, forward strand). Ensembl gene ENSG00000283682.
Homologues: Orthologues: chimpanzee MIR548AH (100% identical), macaque mml-mir-548i (54% identical). Paralogues in human: MIR548AN (84% identical), MIR548H3 (84% identical), MIR548Z (82% identical), MIR548AZ (80% identical), MIR548O2 (80% identical), MIR548AX (79% identical), MIR548X2 (79% identical), MIR548AJ1 (78% identical), MIR548AY (78% identical), MIR548F1 (78% identical), MIR548P (76% identical), MIR548F3 (75% identical), and 13 more.